VIM (vimentin)
Diseases named in the same sentence as VIM in open-access papers (continued):
Sharing a sentence is not in itself a finding about the gene and the disease.
tumor (continued). "Western blot analysis revealed that the expression levels of the protein MMP-9, MMP-2 and Vimentin in tumor tissues of YFTL treatment groups were noticeably lower than that in the MC group." (PMID 30781674, 2019). "When checking the primary tumour, we found increase levels of Ki-67 and vimentin, as well as decreased levels of caspase-3 and E-cadherin." (PMID 31588122, 2019). "Cell cycling proteins CDK4 and cyclin B1 were also reduced, as were markers for epithelial–mesenchymal transition (EMT) and fibronectin in both tumor types but vimentin was reduced in tumors induced by B16-F10." (PMID 31615091, 2019). "CD34/PAS staining indicated that VM was significantly increased in the OE-Gal-1 group, and immunostaining showed positive vimentin staining in both the tumor stroma and tumor cells, while E-cadherin staining was negative in those samples." (PMID 31772662, 2019). "IF protein expression often becomes altered under inflamed tissue settings relative to homeostatic controls; such is the case for keratins in tumor-derived epithelia, as well as for vimentin and nestin in immune cell populations." (PMID 31126068, 2019). "Immunofluorescence assays showed that Prx II and vimentin expression levels were reduced in vivo in miR-122-transfected tumor tissues compared with miR-NC-transfected tumor tissues, indicating that miR-122 targets Prx II and inhibits the EMT in A549/GR tumors." (PMID 30341415, 2019). "A tissue biopsy conducted by a dentist revealed a poorly differentiated tumor, and the immunostaining revealed that the tumor cells were positive for vimentin, CKAE1/AE3 and Ki-67." (PMID 31500651, 2019). "Reduced expressions of N-cadherin and vimentin were found to be associated with EMT process, CCA progression and aggressive clinical outcomes such as poor overall survival and advanced-stage tumor." (PMID 31284679, 2019). "1, MUC-1), etc., CTSC surface markers include CD26, CD44, CD133 and CXC chemokine receptor 4 (CXCR4), etc., circulating EMT positive tumor cell surface markers are vimentin, fibronectin, calcium adhesion protein-N and calcium adhesion protein-O and so on." (PMID 31767014, 2019). "Considering that the invasive tumor cells were positive for vimentin, Snail and TGF-β2, we concluded that their invasion is the result of activation of EMT mechanisms." (PMID 30893803, 2019). "Many studies have examined the surface expression of vimentin in cell types including fibroblasts, endothelial cells, malignant tumor cells, and circulating tumor cells (CTCs)." (PMID 31814834, 2019). "Analysis of patient tumor samples revealed that vimentin is expressed abundantly in GBM, and is prognostic especially in lower grade tumors." (PMID 30987208, 2019). "The authors suggested that epithelial-mesenchymal transition evaluated by E-cadherin, β-catenin, vimentin and Wnt is a late event in tumor progression." (PMID 31850082, 2019). "YFTL significantly reduced MMP-2, MMP-9, N-cadherin and Vimentin expression, but markedly increased E-cadherin expression in the tumor and lung tissues of tumor-bearing mice compared with the MC group." (PMID 30781674, 2019). "CAFs can be classified as vimentin (+) fibroblasts, which infiltrate the tumor; and smooth muscle actin (SMA) (+) myofibroblasts, which predominantly form a capsule-like structure surrounding each CCA nodule." (PMID 30741922, 2019). "We also detected E-cadherin and vimentin expression in xenograft tumor tissues by immunohistochemistry." (PMID 30626446, 2019). "Statistical analysis showed that the expression levels of KLF4 and vimentin are negatively correlated in normal mucosa (P < 0.05) and in tumor sections (P < 0.001)." (PMID 32566755, 2019).
tumor (continued). "Anti‐MMP9 antibody increased the levels of tumour‐associated IL‐28 (1.5‐fold) and decreased stromal markers (collagen I, αSMA) and the EMT marker vimentin." (PMID 30941918, 2019). "TRPM7 silencing increased the levels of E-cadherin, but decreased the levels of N-cadherin, Vimentin and Twist expression in tumor tissues." (PMID 30819230, 2019). "Immunohistochemistry of CRbCs showed strong cytoplasmic paranuclear positivity for vimentin in the majority (≥75%) of tumor cells in five cases and in significant areas ((≥30%) of two cases." (PMID 31455041, 2019). "Immunohistochemically the tumor cells are frequently stained diffusely positive for vimentin and most are positive for epithelial membrane antigen and/or cytokeratine." (PMID 31022624, 2019). "The decrease in E-cadherin and up-regulation of vimentin are the main markers of tumor cell EMT events." (PMID 31754326, 2019). "Meanwhile, the locations of CTSL and Vimentin in tumor cells were investigated by immunohistochemical staining." (PMID 30732622, 2019). "Expression of vimentin in tumor cells undergoing metastasis is considered a marker of epithelial to mesenchymal transition (EMT) (Hay, 2005; Mendez, Kojima & Goldman, 2010)." (PMID 30627484, 2019). "It is easy and simple way to estimate the tumor cell population in PDCs by analyzing EpCAM and vimentin immunofluorescence intensity." (PMID 31850215, 2019). "We correspondingly observed a loss of E-cadherin expression and gain of N-cadherin, vimentin, and AXL expression in the acquired-resistant tumour for patient #4612." (PMID 31653970, 2019). "In tumor cells, diffusive staining of thyroid transcription factor-1, vimentin, and S-100 was assessed by IHC." (PMID 31689841, 2019). "Increased miR-1275 expression inhibited GC metastasis by regulating vimentin/E-cadherin via direct suppression of JAZF1expression, suggesting that miR-1275 is a tumour-suppressor miRNA with the potential as a prognostic biomarker or therapeutic target in GC." (PMID 31357957, 2019). "EMT is characterized by decreasing of E-cadherin expression and increasing of N-cadherin and Vimentin expression in tumor cells." (PMID 30973923, 2019). "In the ccRCC tumor tissues, PDGFRβ was present in the vimentin-positive stroma cells surrounding the tumor islands and blood vessels." (PMID 31690270, 2019). "Immunohistochemical staining was performed to observe the expression of E-cad, N-cad and Vimentin in tumor foci." (PMID 31772677, 2019). "Vimentin can have a further role in such treatments by directing therapeutic agents directly to the tumour site." (PMID 30248895, 2018). "The myoepithelial tumor cells had variable immunohistochemical expression that included not only cytokeratin but also actin, glial fibrillary acid protein, S100, and vimentin." (PMID 29560294, 2018). "In the present study, all cases exhibited PAS-positive granules in the tumor cells alongside positive staining for S-100 protein and vimentin." (PMID 29329562, 2018). "Hugwil reported that a human monoclonal antibody, CLN-IgG, recognized vimentin expressing on the cell surface of the malignant tumor to reprogram cancer stem cells to normal organogenesis and thereby suppressed the progression of cancer." (PMID 29955607, 2018). "High E‐cadherin score and low vimentin score were considered as epithelial type tumor, while low E‐cadherin score and high vimentin score were considered as a mesenchymal type tumor in the present study." (PMID 29855157, 2018). "Vimentin-expressing cells in the interstitium and infiltrating non-tumor cells were excluded from the analyses based on their morphology combined with intense and homogeneous antigen expression." (PMID 30275505, 2018). "We also observed EMT in canine invasive tumors, with numerous tumor cells expressing E-cadherin and vimentin simultaneously." (PMID 30223484, 2018).
tumor (continued). "In human specimens, the downregulation of HMGA1, E2F1, and vimentin, analyzed by IHC, compared with the basal levels found in the biopsies revealed that trabectedin therapy reduces the mesenchymal markers of the tumor." (PMID 29980789, 2018). "The metaplastic CTLA-4+/Vimentin+ tumor cells likely derived from an epithelial mesenchymal transition process and trans-differentiation of spindle cells that have up-regulated mesenchymal markers." (PMID 29682176, 2018). "Expression levels of N-Cadherin, Fibronectin and Vimentin were significantly downregulated (p < 0.05) in the tumours derived from the miR-200b-overexressing MDA-MB-231 (miR200) cells compared to the tumours from the control (Scram) counterparts (respectively)." (PMID 29743493, 2018). "Stochastic expression of the epithelial-to-mesenchymal (EMT) marker vimentin was observed around one edge of cell nuclei in both the seeded tumour fragment and in cells that had migrated into the scaffold." (PMID 30139956, 2018). "In contrast, the proportion of cells expressing vimentin intermediate filaments varied depending on the tumor and culture medium." (PMID 29967607, 2018). "Immunohistochemical analysis revealed that tranilast treatment markedly inhibited migration of the vimentin-positive tumour cells into the host brain tissue, suggesting that tranilast suppresses sNF96.2 cell invasion in vivo." (PMID 29666462, 2018). "The tumour cells in our report showed positive staining forepithelial membrane antigen and vimentin, which further supported the diagnosis." (PMID 31489219, 2018). "Histological analysis revealed a remarkable accumulation of vimentin-positive MSCs in concordance with abundant penetration of T cells inside the Bcr-Abl+ tumor tissue of the Sipa1−/− host." (PMID 29500416, 2018). "Overexpression of vimentin in cancer correlates well with accelerated tumor growth, invasion, and poor prognosis." (PMID 30558247, 2018). "In EMT, as primarily described in experimental studies, the tumour cells downregulate adherence proteins, lose contact to cells, and change to a mesenchymal phenotype, often by exchanging keratin for vimentin or α-actin." (PMID 29976164, 2018). "Compared with the blank and NC groups, the expression of miR-135a, β-catenin, cyclinD1 and vimentin was higher, and cell proliferation, migration, invasion and tumor growth were increased in the miR-135a mimics and siRNA-GSK3β groups." (PMID 29350680, 2018). "By contrast, the majority of BxPC-3 cells maintained prominent E-cadherin expression, with a subpopulation of vimentin-expressing cells found at the tumor-tissue boundary and invading the tissue compartment." (PMID 30158688, 2018). "These tumor foci formed in the lungs of the control group exhibited strong IHC staining of vimentin in contrast to vimentin negativity in lung tissue." (PMID 29350614, 2018). "Epithelial-mesenchymal transition (EMT), a critical process for tumor migration and metastasis, was increased that shown as decrease of epithelial marker E-cadherin and increase of mesenchymal marker vimentin by overexpression of miR-221-5p." (PMID 29506516, 2018). "Vimentin is also a marker for epithelial to mesenchymal transition and has a significant role in tumor metastasis." (PMID 29880757, 2018). "An increased expression of vimentin was observed in malignant tumor cells, which were characterized by chromosomal aberrations." (PMID 29880757, 2018). "Fifteen days post‐implantation, five animals of each group were sacrificed and brains isolated for immunofluorescence (IF) staining of tumor cells (vimentin) and vessels (CD31)." (PMID 29311133, 2018). "As MDA-MB-468 cells expressed the high levels of vimentin, IHC results have confirmed that these tumor foci found in lungs were derived from metastasis of MDA-MB-468." (PMID 29350614, 2018). "The use of tumor markers like keratin, vimentin, and EMA, and electron microscopy can confirm the diagnosis." (PMID 30409199, 2018).
tumor (continued). "While vimentin showed stromal staining, phage was immunoreactive to the tumor cells with robust staining around the invasive or leading edge of the tumor-stromal interaction." (PMID 30619759, 2018). "The tumour cells were positive for vimentin and exhibited patchy positive staining for GFAP and S-100, as well as focal positivity for EMA." (PMID 29348602, 2018). "The treatment with phloroglucinol 39 (25 mg/kg b.w.)administrated four times on alternate days, attenuated the primary tumor formation in mammary fat pads, and attenuated the lung metastasis and the expression levels of vimentin (VIM) and SLUG proteins." (PMID 30373208, 2018). "We then assessed the role of the PI3K p110δ in macrophages in controlling cancer cells metastasis by determining the tumour cell blood burden and the expression of vimentin in the lungs." (PMID 29880805, 2018). "In total, 27 (60%) tumor samples revealed a high vimentin but low E-cadherin expression pattern, while 10 (22.2%) showed a co-expression of both proteins." (PMID 29596469, 2018). "Total mRNA was isolated from tumor cells treated with exosomes and qRT–PCR was performed to evaluate gene expression of Vimentin, N-Cadherin, Snail, Twist, Slug and ZEB-1 in recipient cells." (PMID 29854876, 2018). "Tumors also exhibited rearrangement of cytoskeletal proteins, including β-catenin, keratin 5, and vimentin, depending on tumor progression." (PMID 30652068, 2018). "In various model systems, silencing of p21 increased mesenchymal features, including vimentin, fibronectin, N-cadherin, Slug, and Zeb1 expression, and increased tumor cell migration and invasiveness." (PMID 29774202, 2018). "Immunohistochemical analysis revealed that the tumor was positive for vimentin and partly positive for desmin and cytokeratin CAM5.2." (PMID 29380091, 2018). "Immunohistochemical analysis indicated positivity of the tumour cells for vimentin, CK, EMA, CEA, CKH, GATA3, and P63 and negativity for Desmin, S-100, and CK20." (PMID 29653574, 2018). "Apart from this, the expression level of CSCs‐related proteins:CD44, ALDH1, KLF4, SOX2 and EMT‐related proteins: Slug, Vimentin were also remarkably elevated in mice SCCHN tumour than that in wild‐type normal tongue tissue." (PMID 29193723, 2018). "Tumor tissue had a higher proportion of women with strong vimentin expression than normal tissue 121/279 (43%) vs. 33/279 (12%); the correlation between normal and malignant tissue was 0.11 (95% CI -0.02-0.24)." (PMID 30497427, 2018). "Human origin of tumoral cells was determined by analysis of human-specific vimentin immunostaining and c-Fos expression of tumor cells." (PMID 30353072, 2018). "Because overexpressed Nup88 in tumor tissues is observed in the cytoplasm, we anticipated that Nup88 would colocalize with vimentin in the cytoplasm." (PMID 29724197, 2018). "Vimentin expression in normal mucosa was restricted to infiltrating mesenchymal cells and was up-regulated in tumor-adjacent mucosa with hyper- and/or dysplastic cells." (PMID 30275505, 2018). "The intrahepatic tumour nodules were then evaluated for expression of E‐cadherin, Vimentin, Snail+Slug, MMP2 and Smad4 by immunohistochemical analysis." (PMID 29148232, 2018). "In order to examine the correlation between EMT status and the PD‐L1 expression on tumor cells, IHC for E‐cadherin, vimentin, and PD‐L1 was performed in TMA and FFPE tissue samples of ESCC." (PMID 29855157, 2018). "Univariate analysis revealed that this EMT phenotype (i.e., elevated Gal-3 and vimentin expression) are predictors of tumor recurrence and survival." (PMID 29562695, 2018). "Immunohistochemical staining revealed that the tumor was positive for vimentin and partly positive for cytokeratin CAM5.2." (PMID 29380091, 2018).
tumor (continued). "The expression of E-cadherin is negatively correlated with tumor invasiveness, and the disappearance of epithelial cell polarity is accompanied by an increase in the expression of mesenchymal cell markers vimentin, N-cadherin, and fibronectin." (PMID 29531823, 2018). "Guiping Qin demonstrated that the tumor cells are positive for vimentin, CK, CgA, syn, CEA, calcitonin, HMB-45, and S-100 and negative for TG and TTF-1." (PMID 30424779, 2018). "Accordingly, IHC analysis revealed that S100A6, lumican, plastin-2 and 14-3-3 zeta/delta were expressed in the cytoplasm of tumor cells while vimentin was found mainly in the cytoplasm of fibroblasts in periductal fibrotic tissue and tumor stroma." (PMID 30440021, 2018). "In case 1, vimentin was expressed in both tumor tissues and CTCs, suggesting that EMT led to off-target resistance to ALK inhibitor." (PMID 29844868, 2018). "In 9 carcinomas within the vascular walls and at the invasion front, several tumour cells were positively stained for vimentin but still connected to the main tumour cell bulk." (PMID 29976164, 2018). "Immunohistochemistry on tumor sections with a human vimentin antibody confirmed the presence of human MSCs within peritoneal tumoral nodes." (PMID 29455640, 2018). "Two cytoskeletal related proteins, vimentin and plectin, which are known tumor biomarkers, were also upregulated in IDC samples compared to normal tissue." (PMID 30154546, 2018). "Mutually exclusive expression of EpEX and vimentin was recurrently observed at the interface of the tumor area to interstitium." (PMID 30275505, 2018). "Our immunohistochemical examination of skeletal proteins also suggested that the appearance and distribution of the immunomarkers, β-catenin, keratin 5, and vimentin, are dependent on tumor progression." (PMID 30652068, 2018). "In further support of this, our analysis of the TCGA database revealed that EPHB6 expression negatively correlates with that of vimentin in TNBC tumours." (PMID 29700392, 2018). "One drug that can interfere with vimentin is withaferin-A, a compound that is known for its anti-tumour and anti-angiogenic activities." (PMID 30248895, 2018). "The undifferentiated tumour cells showed loss of E-cadherin and HMWC and were positive for vimentin and pan-cytokeratin expression." (PMID 29144834, 2018). "In terms of EMT protein expression, 10.05 tumor cells maintained prominent E-cadherin, while CAFs stained strongly for vimentin." (PMID 30158688, 2018). "The most characteristic feature of the Mes-like group of tumors is tumor cell expression of VIM and ZEB2, markers for a mesenchymal phenotype." (PMID 29487377, 2018). "In contrast, most TN tumors contained numerous K19, K14, and VIM-defined differentiation states, including robust proportions of epithelial tumor cells expressing more than one of these differentiation-state markers." (PMID 30232459, 2018). "The dynamic properties of the intermediate filament protein vimentin are very important for cell flexibility and increased expression of vimentin is an important sign of EMT in tumor invasion and metastasis." (PMID 30157906, 2018). "In parallel, the western blotting or immunohistochemical staining (IHC) analysis revealed that the protein expression levels of MAPK1, Snail, Slug, and vimentin were lower in the tumor tissues from the miR-22 group than that in the NC group." (PMID 29434190, 2018). "The tumour was composed of sarcomatous and carcinomatous elements, and immunohistochemical examination showed that tumour cells were positive for cytokeratin, epithelial membrane antigen, vimentin, and GATA3 markers." (PMID 29653574, 2018). "In order to look for evidence of EMT in the NSCLC specimens we quantified E-cadherin levels in the tumour cells by H-Score analysis and also scored them for expression of the mesenchymal marker vimentin." (PMID 29416729, 2018).